RAD51 (RAD51 recombinase)
Diseases named in the same sentence as RAD51 in open-access papers (continued):
Sharing a sentence is not in itself a finding about the gene and the disease.
COVID-19 (1 paper, 2023). A disease caused by infection with severe acute respiratory syndrome coronavirus 2. "Elevated levels of inflammation are associated with severe COVID-19, and RAD51 has been shown to modulate inflammatory signaling pathways." (PMID 37234545, 2023). "In conclusion, further research is needed to fully elucidate the mechanisms of RAD51 for understanding the common pathogenic processes between COVID-19 and HFRS, which could pave the way for the development of novel therapeutic strategies." (PMID 37234545, 2023). "Previous studies demonstrated a potential association between RAD51 and COVID-19." (PMID 37234545, 2023). "Our study uncovered six genes named RAD51, ALDH1A1, UBA52, CUL3, GADD45B, and CDKN1A were found to be commonly dysregulated among HFRS and COVID-19." (PMID 37234545, 2023). "The protein–protein interaction (PPI) network of DEGs was then constructed and six genes named RAD51, ALDH1A1, UBA52, CUL3, GADD45B, and CDKN1A were identified as the commonly dysregulated hub genes among HFRS and COVID-19." (PMID 37234545, 2023).
cyst (1 paper, 2025). A sac-like closed membranous structure that may be empty or contain fluid or amorphous material. "In addition, RH tachyzoites can form cyst-like structures in vitro, either after treatment with the RAD51 inhibitor B02 or even spontaneously in skeletal muscle cell cultures." (PMID 41346605, 2025).
DNA repair deficiency (1 paper, 2019). "Based on the results presented, we suggest considering genetic testing for RAD51 and XRCC3 to identify those men who have DNA repair deficiency and who have not responded to standard treatment." (PMID 31186630, 2019).
dysplasia (1 paper, 2021). A usually neoplastic transformation of the cell, associated with altered architectural tissue patterns. "Knockdown of TONSL by siRNA treatment in patient cells from SPONASTRIME dysplasia, a rare weak bone disease caused by hypomorphic mutation of TONSL, reduces RAD51 foci upon CPT treatment, revealing its essential role in RAD51’s ability to load to DNA damage sites by interacting with RPA." (PMID 33498235, 2021).
emphysema (1 paper, 2019). "However, we did not detect differences in RAD51 expression in ATII cells isolated from emphysema patients in comparison with controls." (PMID 30696938, 2019). "However, we did not detect significant differences in RAD51 levels in ATII cells isolated from non-smokers, smokers and patients with emphysema." (PMID 30696938, 2019).
ependymoma (1 paper, 2018). A WHO grade II, slow growing tumor of children and young adults, usually located intraventricularly. "We also found RAD51, another DNA repair gene, was up-regulated in supratentorial and infratentorial ependymomas." (PMID 29416789, 2018). "In this study, we validated the higher level of CCND1 and RAD51 in ependymoma especially the tumors located on supratentorium." (PMID 29416789, 2018). "By analyzing high throughput gene expression microarray followed by qRT-PCR validation of ependymoma tissues, we proved CCND1 and RAD51 upregulation in both primary and recurrent ependymomas." (PMID 29416789, 2018).
Ewing sarcoma (1 paper, 2022). A small round cell tumor that lacks morphologic, immunohistochemical, and electron microscopic evidence of neuroectodermal differentiation. "The number of RA51 foci-positive cells was compared among these cell lines, which clearly indicates that RAD51 focus formation in TL+ Ewing sarcoma cells is at the same level as in MMR-deficient DLD-1 cells." (PMID 36042341, 2022). "More remarkably, numerous RAD51 foci were similarly observed also in TL+ Ewing sarcoma cell lines, WE-68 and SK-N-MC." (PMID 36042341, 2022). "The two Ewing sarcoma cell lines, WE-68 and SK-N-MC, were next to them, although RAD51 expression being relatively low in the latter." (PMID 36042341, 2022). "Using comprehensive microarray approaches, we observed that expression of the HR genes, particularly of RAD51, is upregulated in TL+ Ewing sarcoma cell lines, WE-68 and SK-N-MC, as in the other TL+ tumor cell lines and one defective in DNA mismatch repair (MMR)." (PMID 36042341, 2022).
familial breast cancer (1 paper, 2014). "We discovered several well-established cancer mutations in single samples, including a BRAF V600E mutation (cell line A673), a PI3KCA mutation (cell line ES4) that has been recurrently found in multiple cancer types, and a RAD51 alteration (tumor EWS101) associated with familial breast cancer." (PMID 25010205, 2014).
Fibroadenoma (1 paper, 2011). A benign tumor of the breast characterized by the presence of stromal and epithelial elements. "The levels of RAD51 were much lower in HNF, hMSC (human mesenchymal stem cells derived from umbilical cord) and XWXL (fibroblasts derived from a benign fibroadenoma) than those in ESCC cells." (PMID 21858113, 2011).
folate deficiency (1 paper, 2015). A nutritional condition produced by a deficiency of FOLIC ACID in the diet. "Next, we studied RAD51 foci formation in response to folate deficiency." (PMID 26197802, 2015).
Gynecomastia (1 paper, 2020). Abnormal development of large mammary glands in males resulting in breast enlargement. "RAD51 and XRCC3 exhibited consistent staining patterns both in gynecomastia and female breast normal tissue: Intense positive nuclear and cytoplasmatic staining was found for RAD51 in all samples, whereas negative nuclear staining and a weak cytoplasmatic staining was observed for XRCC3." (PMID 32295201, 2020).
hantavirus infection (1 paper, 2023). "In the same vein, RAD51 might play a role in the virus-host interaction by reducing viral replication during hantavirus infection." (PMID 37234545, 2023).
hyperlipidemia (1 paper, 2022). "Among the investigated SNPs, only RAD51 genetic variability was associated with NYHA class, even after adjusting for the presence of hyperlipidemia and higher BMI that were associated with higher NYHA class." (PMID 36139526, 2022). "Carriers of RAD51 rs1801321 TT genotype were more likely higher NYHA class in the univariable analysis (OR = 10.0, 95% CI = 1.63–61.33, p = 0.013) and after adjustment for hyperlipidemia and BMI (OR = 9.27, 95% CI = 1.28–67.02, p = 0.027)." (PMID 36139526, 2022).
idiopathic pulmonary arterial hypertension (1 paper, 2018). A sporadic form of pulmonary arterial hypertension (PAH) characterized by elevated pulmonary arterial resistance leading to right heart failure. "Similarly, immunohistochemistry of lung sections from idiopathic pulmonary arterial hypertension patients showed 76% reduction of RAD51 (P = 0.0038) in the endothelium of pulmonary arteries compared to control samples." (PMID 30272025, 2018). "Reduction of RAD51 is observed not only in pulmonary microvascular endothelial cells but also in pulmonary artery smooth muscle cells isolated from rats with heterozygous BMPR2 mutation and from human idiopathic pulmonary arterial hypertension patients." (PMID 30272025, 2018).
Immunodeficiency (1 paper, 2022). Failure of the immune system to protect the body adequately from infection, due to the absence or insufficiency of some component process or substance. "Germline mutations in the FANCI and RAD51 genes might impair the patient’s DNA repair ability, leading to a degree of immunodeficiency and tumour susceptibility." (PMID 35280783, 2022). "However, germline mutations in the FANCI and RAD51 genes might impair the DNA repair ability, lead to a certain degree of immunodeficiency and tumour susceptibility of the patients, and thereby make the patients sensitive to pathogen infection, ionizing radiation, and other damages." (PMID 35280783, 2022).
in situ carcinoma (1 paper, 2014). A malignant epithelial neoplasm which is confined to the epithelial layer without evidence of further tissue invasion. "Moreover, in 23 cases of matched in situ carcinoma, invasive carcinoma and LN metastases from the same patients, RAD51 levels increased with higher stage lesions (p=0.003)." (PMID 24811120, 2014).
intraductal carcinoma (1 paper, 2022). "This variant was found on the mammary gland of a male dog, described as intraductal carcinoma, located in one of the BRCA repeats critical for binding to RAD51." (PMID 35743882, 2022).
invasive ductal carcinoma of the breast (1 paper, 2022). "Overexpression of RAD51 was also associated with the histological classification of invasive ductal carcinoma of the breast and was proposed as a potential diagnostic and prognostic biomarker." (PMID 36139526, 2022).
leiomyoma (1 paper, 2024). A well-circumscribed benign smooth muscle neoplasm characterized by the presence of spindle cells with cigar-shaped nuclei, interlacing fascicles, and a whorled pattern. "The results of our study showed that RAD51::NUDT3 fusion can occur in both usual and cellular leiomyoma." (PMID 37466765, 2024). "In conclusion, our study showed that RAD51::NUDT3 fusion can occur in both usual and cellular leiomyoma." (PMID 37466765, 2024).
Miscarriage (1 paper, 2024). A pregnancy that ends at a stage in which the fetus is incapable of surviving on its own, defined as the spontaneous loss of a fetus before the 22th week of pregnancy. "Collectively, these results showed that HR repair, as indicated by lower levels of BRCA1 and RAD51 and higher levels of DSB, was suppressed in RM versus HC villous tissues and the defective HR repair in villous tissues was associated with miscarriage." (PMID 38286681, 2024).
myxofibrosarcoma (1 paper, 2025). A malignant fibroblastic neoplasm arising from the soft tissue. "Of note, a patient with myxofibrosarcoma who had an ongoing deep and sustained response harbored a mutation in PALB2, which is involved in the recruitment of BRCA2 and RAD51 to DNA breaks in the homologous recombination pathway." (PMID 41145467, 2025).
Nijmegen breakage syndrome (1 paper, 2024). Nijmegen breakage syndrome is a rare genetic disease presenting at birth with microcephaly, dysmorphic facial features, becoming more noticeable with age, growth delay, and later-onset complications such as malignancies and infections. "To specifically investigate the impact of NBS1-P112 on DNA repair we expressed FLAG-NBS1 constructs (WT and P112G) in NBS-ILB1 Nijmegen breakage syndrome patient-derived fibroblasts, and examined these lines for HU-induced NBS1 and RAD51 foci formation." (PMID 38943005, 2024).
non-Hodgkin lymphoma (1 paper, 2011). Distinct from Hodgkin lymphoma both morphologically and biologically, non-Hodgkin lymphoma (NHL) is characterized by the absence of Reed-Sternberg cells, can occur at any age, and usually presents as a localized or generalized lymphadenopathy associated with fever and weight loss. "The HDAC inhibitor, PCI-24781, after treatment of Hodgkin and non-Hodgkin lymphoma cells with a PARP inhibitor, resulted in a synergistic increase in apoptosis and a decrease in RAD51 expression." (PMID 21854619, 2011).
Obesity (1 paper, 2024). Accumulation of substantial excess body fat. "Maternal obesity did not alter quantity of RAD51 and RPA2 foci in leptotene and zygotene oocytes." (PMID 38868907, 2024).
osteoarthritis (1 paper, 2016). A noninflammatory degenerative joint disease occurring chiefly in older persons, characterized by degeneration of the articular cartilage, hypertrophy of bone at the margins and changes in the synovial membrane. "No direct links have been established between RAD51 and osteoarthritis pathogenesis." (PMID 27802335, 2016).
osteoporosis (1 paper, 2022). A condition of reduced bone mass, with decreased cortical thickness and a decrease in the number and size of the trabeculae of cancellous bone (but normal chemical composition), resulting in increased fracture incidence. "The results showed that RAD51 was downregulated in osteoporosis, but upregulated in differentiated osteoblasts." (PMID 35176943, 2022). "The bone mineral density (BMD) in the HU group was lower than that in the NC group; however, RAD51 alleviated the development of osteoporosis." (PMID 35176943, 2022). "Overexpression of RAD51 facilitated osteoblastogenesis and suppressed osteoclastogenesis, suggesting that RAD51 might alleviate osteoporosis." (PMID 35176943, 2022). "Moreover, RAD51 suppressed osteoporosis in vivo, suggesting that RAD51 is beneficial for suppressing the development of osteoporosis." (PMID 35176943, 2022). "In short, the expression of RAD51 is decreased in osteoporosis." (PMID 35176943, 2022). "Our future study will explore the clinical effect of RAD51 on osteoporosis." (PMID 35176943, 2022). "It is the first study to show that RAD51 is involved in the progression of osteoporosis." (PMID 35176943, 2022). "This study provides a basis for RAD51 to become the target of treatment osteoporosis." (PMID 35176943, 2022). "In the present study, RAD51 was found to be dysregulated in osteoporosis." (PMID 35176943, 2022). "This study provides a basis for the future prospect of RAD51 treating osteoporosis." (PMID 35176943, 2022). "The effect of RAD51 on osteoporosis was also explored in vivo." (PMID 35176943, 2022). "We investigated the role of RAD51 in osteoporosis and the molecular mechanism." (PMID 35176943, 2022). "To further verify the potential role of RAD51 in osteoporosis, we performed an in vivo assay." (PMID 35176943, 2022). "Furthermore, qPCR illustrated that RAD51 expression was significantly decreased in the serum of patients with osteoporosis." (PMID 35176943, 2022). "In this study, the expression of RAD51 was found to be decreased in patients with osteoporosis." (PMID 35176943, 2022). "However, little is known about the role of RAD51 in osteoporosis." (PMID 35176943, 2022). "Here, we speculated that RAD51 is involved in the development of osteoporosis." (PMID 35176943, 2022). "However, the involvement of ATM/ATR and the relationship between RAD51 and ATM/ATR in osteoporosis remains unknown." (PMID 35176943, 2022). "However, the role of RAD51 and its interaction with ATM/ATR in osteoporosis remains unclear." (PMID 35176943, 2022).
ovarian clear cell cancer (1 paper, 2014). An invasive malignant neoplasm that arises from the ovary and is characterized by a predominance of clear and hobnail malignant epithelial cells. "Elevated expression of miR-107 has been correlated with PARP inhibitor sensitivity and reduced RAD51 expression in a subset of ovarian clear cell carcinomas." (PMID 25313363, 2014).
ovarian dysfunction (1 paper, 2019). The inability of the ovaries to function. "The HOP2-MND1 complex has also been implicated in ovarian dysfunction and biochemically, is capable of driving RAD51-mediated alternative lengthening of telomeres in somatic cells." (PMID 31830031, 2019).
peritoneal mesothelioma (1 paper, 2021). A benign or malignant mesothelial neoplasm that arises from the peritoneum.
pneumonia (1 paper, 2025). An acute, acute and chronic, or chronic inflammation focally or diffusely affecting the lung parenchyma, caused by an infection in one or both of the lungs (by bacteria, viruses, fungi, or mycoplasma.). "The downregulation of apoptosis-related genes such as TOP2A and RAD51 may promote cell survival and tissue repair, contributing to the recovery from pneumonia." (PMID 41000417, 2025).
Primary amenorrhea (1 paper, 2020). "In women, complete loss of BRCA2 function leads to ovarian dysgenesis resulting in primary amenorrhea, with reduced Rad51 function in HR indicated by low Rad51 expression at the site of DNA damage." (PMID 31947601, 2020).
primary immunodeficiency (1 paper, 2025). "The positive correlation between RAD51 and primary immunodeficiency observed in this study may reflect a compensatory enhancement of DNA repair mechanisms in response to sustained replication stress." (PMID 40746357, 2025).
progeria (1 paper, 2023). "Similarly, in vivo partial reprogramming studies show a more robust improvement to lifespan in progeria models indicating an ability to respond to deleterious cell states Previously, it was shown improved DNA repair via overexpression of the HR protein Rad51 enhances reprogramming efficiency." (PMID 38322248, 2023).
prostate adenocarcinoma (1 paper, 2021). "Compared with normal samples, EXO1, RMI2, and RAD51 were significantly overexpressed in most cancer types including BRCA, while RMI2 was significantly lower expressed in PARD (Prostate adenocarcinoma)." (PMID 34408776, 2021).
psoriasis (1 paper, 2022). An autoimmune condition characterized by red, well-delineated plaques with silvery scales that are usually on the extensor surfaces and scalp. "We then used the RT-qPCR technique to assess the transcript levels of Rad51 and of Ribonuclease HII (RNase HII) in patients with psoriasis." (PMID 35327560, 2022). "While the decrease in the level of transcripts in RNase HII is highly significant especially in the LA tissues of psoriasis patients, in contrast the levels of Rad51 transcripts do not seem to increase." (PMID 35327560, 2022).
pterygium (1 paper, 2021). A wedge-shaped fibrovascular lesion arising from the bulbar conjunctiva and extending to the cornea. "In addition, PLK1, which regulates the activity of RAD51, was identified as highly expressed in pterygium." (PMID 34769520, 2021). "It was previously reported that genes involved in double-strand DNA break repair, RAD50, RAD51, XRCC2 and XRCC3, are differentially expressed in pterygium." (PMID 34769520, 2021).
renal carcinoma (1 paper, 2016). A carcinoma arising from the epithelium of the renal parenchyma or the renal pelvis. "We consistently observed inverse relationships between the expression of SET domain-containing proteins and the expression of Rad51 in different classes of renal carcinoma." (PMID 27170370, 2016).
Renal cyst (1 paper, 2025). A fluid filled sac in the kidney. "Further examination of differentially expressed genes in renal cysts and SC transplants demonstrated significant downregulation of key meiotic proteins, including Sycp3 and Sycp1, as well as defects in DSB-related proteins Rad51 and Spo11, which align with our previous findings." (PMID 40386496, 2025).
Sertoli Cell-Only Syndrome (1 paper, 2022). A type of male infertility in which no germ cells are visible in any of the biopsied SEMINIFEROUS TUBULES (type I) or in which germ cells are present in a minority of tubules (type II). "Conditional disruption of RAD51 in germ cells by Vasa-Cre led to spermatogonial loss and Sertoli cell-only syndrome." (PMID 35292640, 2022).
squamous cell lung carcinoma (1 paper, 2020). A carcinoma arising from squamous bronchial epithelial cells. "Activation of HRR pathways, as evidenced by Rad51 expression, was assessed in SG-sensitive cell lines with low and moderate Trop-2-expression (SK-MES-1 squamous cell lung carcinoma and HCC1806 TNBC, respectively), compared to a low Trop-2-expressing, less SG-sensitive TNBC cell line (MDA-MB-231)." (PMID 33196706, 2020).
Testis (1 paper, 2022). "Testis cancer had strong RAD51 staining but some cell components of the normal testis tissue also had strong signals." (PMID 35359409, 2022).